MMP9 (matrix metallopeptidase 9)
Diseases named in the same sentence as MMP9 in open-access papers (continued):
Sharing a sentence is not in itself a finding about the gene and the disease.
endometriosis (continued). "Recently, a higher mRNA expression of MMP2 and MMP9 was detected in menstrual blood-derived stromal cells from women with endometriosis compared to patients without endometriosis." (PMID 37893104, 2023). "Based on previous studies, it is shown that patients with endometriosis have much more active types of MMP-9 in epithelial cells and menstrual stroma than those without endometriosis." (PMID 35059465, 2022). "A positive correlation between c-fos and MMP-9 protein levels was found, which suggests that c-fos may be regulated by sex hormones and promote the gene expression of MMP-9 in the development of endometriosis." (PMID 35280869, 2022). "We believe that the beneficial effects of metformin in the treatment of endometriosis is a result of combination of diminishment endometrial lesions through suppression of VEGF and MMP9, and improvement of uterus conditions for implantation via LIF upregulation." (PMID 35273494, 2022). "The correlation between an increase in MMP-9 expression and increase in endometriosis has been confirmed in clinical studies and reduction in MMP-9 levels has been suggested as an important clinical biomarker for endometriosis treatment effectiveness." (PMID 35273494, 2022). "Pan found that both c-fos and MMP-9 protein levels were higher in females with endometriosis than in those without endometriosis." (PMID 35280869, 2022). "Increased expression of MMP9 colocalizing with CD68 + cells may correspond to the enhanced detachment capacity and mobility of eutopic endometrium in endometriosis." (PMID 34068967, 2021). "According to the findings, resveratrol may ameliorate endometriosis progression through reducing the expression of VEGF, TGF-β, and MMP-9 in endometrial stromal cells (ESCs)." (PMID 33723310, 2021). "This study showed that MMP-9 is expressed in menstruated endometrial epithelial cells in women with and without endometriosis." (PMID 32498419, 2020). "Our study demonstrates a statistically higher expression of MMP-2 and MMP-9 both in ectopic and eutopic endometrium samples compared to samples taken from patients without endometriosis." (PMID 33072202, 2020). "The aim of the study was to evaluate the level of MMP-2 and MMP-9 expression in ectopic and eutopic endometrium of women with visible endometriotic lesions and eutopic endometrium in patients with no signs of endometriosis." (PMID 33072202, 2020). "The aim of the study was to evaluate the level of MMP-2 and MMP-9 expression in the ectopic endometrium of women with visible endometriotic lesions and eutopic endometrium in patients with no signs of endometriosis." (PMID 33072202, 2020). "This study proved that the examination of MMP-9 and TIMP-1 expression in endometrial menstrual blood cells may support the diagnosis of endometriosis." (PMID 32498419, 2020). "Xiaozheng decoction also could relieve dysmenorrhea and pelvic pain and improve qi stagnation and blood removal in endometriosis patients, which may be related to lower levels of CA125, CA199, MMP-3, MMP-9, VEGF, and TNF-α in serum." (PMID 30402122, 2018). "Similarly, induction of endometriosis enhanced the levels of MMP-2 and MMP-9 in peritoneal fluid and cells in an in vivo study using BALB/c mice." (PMID 28264481, 2017). "Our previous study showed significantly higher total and active forms of MMP-9 in the menstrual epithelial and stromal cells of patients with endometriosis compared to those of patients without endometriosis." (PMID 26056600, 2014). "The present study also revealed that menstrual epithelial and stromal cells of patients with endometriosis possessed significantly higher total and active forms of MMP-9 compared to those of patients without endometriosis." (PMID 23626717, 2013). "Total and active forms of MMP-9 were significantly higher in epithelial and stromal cells prepared from menstrual endometrium in patients with endometriosis compared to patients without endometriosis." (PMID 23626717, 2013).
endometriosis (continued). "The topical delivery of GMDP to the peritoneal macrophages by AMNPs led to the enhance the initially reduced membrane expression of SRs by the macrophages of women with endometriosis, increased NOD2 and RAGE mRNAs expression, and also promoted an increase of the expression of MMP-9 mRNA." (PMID 24455738, 2013). "In epithelial and stromal cells prepared from the menstrual endometrium treated with PKF 115–584, total MMP-9 was significantly higher in patients with endometriosis than in patients without endometriosis." (PMID 23626717, 2013). "Recently, it was demonstrated in mice that the treatment of 15-Epi-lipoxin A4 (LXA4) may inhibit the progression of endometriosis possibly by lowering the concentrations and the activities of MMP-2 and MMP-9." (PMID 20085636, 2010). "Thus, we investigated whether PCB126 exposure modulates the SRC-1 isoform/MMP-9/ESR2 axis in endometriotic lesions, enhancing endometriosis progression." (PMID 41054802, 2025). "In a mouse model of endometriosis, PCB-126 exposure significantly promoted the growth of ectopic lesions by activating the Steroid Receptor Coactivator-1 (SRC-1) isoform/Matrix Metalloproteinase-9 (MMP9)/Estrogen Receptor-β (ERβ) axis, a critical pathway driving disease progression." (PMID 40951281, 2025). "Additionally, certain genes that regulate MMP-2, MMP-9, and TGF-β1 may contribute to the elevated expression of these enzymes in endometriosis." (PMID 38398530, 2024). "Specifically, the mechanism of action of MMP-2 and MMP-9 involves the degradation of the extracellular matrix (ECM), which facilitates the infiltration and attachment of endometrial cells to neighboring tissues, ultimately resulting in the development of endometriosis lesions." (PMID 38398530, 2024). "Given that these proteins play an important role in the early pathophysiology of the disease before anatomical abnormalities occur, we hypothesized that MMP-9 and TIMP-1 in endometrial cells isolated from menstrual blood can be used as markers to support the diagnosis of endometriosis." (PMID 32498419, 2020). "During the menstrual phase, the examination of MMP expression in menstrual serum was conducted by Malik (2006), who investigated MMP-2 and MMP-9 by zymography and showed that the expression of the latent and the active forms of MMP-9 were similar in women with endometriosis and in those without." (PMID 32498419, 2020). "Moreover, we also detected the serum levels of proteins associated with cell proliferation, angiogenesis, and epithelial-mesenchymal transition processes which are closely related to the pathogenesis of endometriosis, such as VEGF, MMP-2 and MMP-9,21–23, by ELISA." (PMID 31727934, 2019). "VEGF, VEGFR-2 and MMP-9 immunoreactivity was detected in the lesions, predominantly in the stroma, around the glands, and in the cytoplasm of endothelial cells in non-treated endometriosis." (PMID 27851787, 2016). "Levels of total and active forms of MMP-9 were significantly higher in epithelial and stromal cells prepared from menstrual endometrium in patients with endometriosis compared to patients without endometriosis." (PMID 23626717, 2013). "The recent evidence suggests that ovarian macrophages migration is a result of RANTES secretion into the environment of endometriomas, and their numerous products (IL-1beta, TNF-alfa, Il-6, Il-8, MMP-9, VEGF and others) may be involved in the onset and development of endometriosis." (PMID 16907986, 2006). "Our findings revealed significantly elevated MMP-9 levels and reduced NGAL levels in patients with endometrioma compared with those with unexplained infertility, reinforcing the hypothesis that these biomarkers may play essential roles in the pathophysiology and potential diagnosis of endometriosis." (PMID 40810077, 2025).
endometriosis (continued). "For example, compared with MSCs in women without endometriosis (normal MSCs), MSCs in endometriosis patients (endometriotic MSCs) express higher levels of Cyclin D1, Matrix metalloproteinases (MMP)-2, and MMP-9." (PMID 36358904, 2022). "On the other hand, there was no inverse correlation between MMP-9 and TIMP-1 staining in women with endometriosis (Rs = −0.196, p = 0.30)." (PMID 32498419, 2020). "Several studies have reported higher expression of MMP-2, MMP-9, MMP-14, and MMP-24 in the eutopic endometrium or ectopic lesions of women with endometriosis, as compared to levels in women without endometriosis." (PMID 31636643, 2019). "MMP9 also has activity against type III collagen, the typical collagen found in healthy endometrium; however, it cannot degrade collagen type I which is present in destructive endometriosis." (PMID 37869492, 2023).
lymph node metastasis (104 papers, 1999 to 2026). "Matrix metalloproteinase 9 (MMP-9), associated with lymph node metastasis and reduced survival rates, is synergistically upregulated by pro-inflammatory cytokines and growth factors in an NF-κB-dependent manner." (PMID 40444100, 2025). "High levels of MMP-9 are strongly linked to more tumor invasion, lymph node metastasis, and poor prognosis in CRC patients." (PMID 41154590, 2025). "Some heterogeneities were found in the analysis of the associations of MMP-9 expression with lymph node metastasis, myometrial invasion and vascular invasion of EC, so the random-effects model was used." (PMID 36387161, 2022). "Our meta-analysis demonstrated that MMP2 and MMP9 overexpression in tumor cells was associated with poor survival, larger tumor size, lymph node metastasis, distant metastasis, higher clinical stage, and histological grade in patients with BC." (PMID 33568081, 2021). "Previous studies revealed that MMP9 was significantly associated with poor survival and lymph node metastasis in ICC and various inflammation states." (PMID 34109213, 2021). "Increased MMP-2 and MMP-9 expression in human oral cancer tissues was significantly associated with T-stage and lymph node metastasis." (PMID 32102512, 2020). "Clinical studies have shown that high expression of MMP-9 is associated with clinical pathological features of cancer such as lymph node metastasis and tumor differentiation." (PMID 31038586, 2019). "Our findings indicated that serum MMP-9 is positively associated with tumor size, lymph node metastasis, extrathyroidal invasion, and TNM stage." (PMID 33817161, 2019). "Preoperative serum MMP-9 was associated with Bismuth-Corlette classification) and lymph node metastasis." (PMID 31038586, 2019). "MMP9 expression was significantly associated with lymph node metastasis, histologic type, mitotic count, histologic grade, and snail expression." (PMID 29416639, 2018). "Dysregulation of MMP2 and MMP9 is frequently present in head and neck cancers and is associated with lymph node metastasis and poor prognosis." (PMID 28963552, 2017). "MMP-9 expression in matched epithelium and lymph nodes was associated with lymph node metastasis, and its expression in lymph nodes was positively associated with lymphangiogenesis." (PMID 24845596, 2014). "Only active MMP-9 was significantly associated with extrathyroid invasion, lymph-node metastasis, and the degree of tumor infiltration (P < 0.001, P = 0.004, and P < 0.001, respectively)." (PMID 24778099, 2014). "A previous study showed that higher expression of MMP-9 protein was associated with lymph node metastasis,consistent with our findings." (PMID 24845596, 2014). "MMP-9 expression in matched epithelial tissues and lymph nodes was associated with lymph node metastasis (Mann–Whitney U, P<0.05)." (PMID 24845596, 2014). "The protein expression of MMP-2 and MMP-9 was positively associated with the status of lymph node metastasis and TNM stage (P<0.001)." (PMID 23935727, 2013). "In this study, we also found that MMP9 overexpression was significantly associated with T classification (tumor size), N classification (lymph node metastasis), and clinical stages of NPC patients." (PMID 20534121, 2010). "Previous studies have determined that both MMP-2 and MMP-9 are associated with lymph node metastasis and poor outcome in HNSCC." (PMID 18349846, 2008). "Furthermore, the presence of the T allele, acetylated c-Jun expression, and MMP-9 had a strong tendency to associate with the formation of lymph node metastases, reaching borderline statistical significance." (PMID 36010303, 2022). "The expression of MMP9 was associated with lymph node metastasis in CCA." (PMID 34067437, 2021). "High expression of MMP-9 is associated with lymph nodes metastasis and poor prognosis outcome." (PMID 32127934, 2020).
lymph node metastasis (continued). "Previous study showed that MMP-9 protein was primarily found in the cytoplasm of both cancer and stromal cells and, in another study, its expression in matched epithelium and lymph node was associated with lymph node metastasis." (PMID 27110764, 2016). "In addition, the co-expression of MMP-9 and TN-C was significantly associated with lymph node metastasis, vascular invasion and hepatic metastasis." (PMID 26652622, 2015). "Additionally, increased MMP-9 levels were associated with lymph node metastasis, higher tumor stage, lower relapse-free and overall survival." (PMID 19889214, 2009). "In addition, high MMP-9 expression was significantly associated with lymph node metastasis (OR = 2.98, 95% CI = 1.27 – 7.03, P < 0.05), myometrial invasion (OR = 2.42, 95% CI = 1.42 – 4.12, P < 0.05) and vascular invasion (OR = 2.67, 95% CI = 1.27 – 5.60, P < 0.05) of EC in Asians." (PMID 36387161, 2022). "However, only the expression levels of the proliferation-related genes Cyclin D1 and Cyclin E1 were significantly associated with the lymph node metastasis, and only the Cyclin E1 and MMP9 expression levels showed significant correlation with distant metastasis (M stage)." (PMID 34975298, 2022). "Furthermore, we found that preoperative serum MMP-9 levels were associated with Bismuth-Corlette classification and Lymph node metastasis, which may be related to the lower sensitivity of MMP-9 in predicting the prognosis of HC patients." (PMID 31038586, 2019). "Thus, we hypothesized that the levels of VEGF and MMP-9 may be used as risk factors in predicting lymph node metastasis." (PMID 24944618, 2014). "In HNSCC, elevated MMP9 expression was substantially correlated with lymph node metastases and unfavourable prognosis." (PMID 40475773, 2025). "This is particularly relevant in the context of PTC, where increased MMP-9 expression has been directly correlated with lymph node metastasis and poor prognosis." (PMID 40869275, 2025). "Higher expression levels of MMP-2, MMP-9, and MMP-14 were associated with advanced tumor stage, lymph node metastasis, and poorer prognosis." (PMID 38089632, 2023). "Expression of MMP9 with respect to the presence of lymph node metastasis, tumor grade, and TNM staging." (PMID 36756017, 2023). "Previous studies evaluating the MMP-9 expression associated with the lymph node metastasis of hypopharyngeal carcinoma have revealed that high expression of MMP-9 correlated with the lymph node metastasis and the metastatic lymphatic degree." (PMID 37600570, 2023). "CCR7 significantly regulated the MMP-9 expression and revealed the highest sensitivity to predict the lymph node metastasis in LSCC compared to the MMP-9 protein." (PMID 37600570, 2023). "The odds ratio (OR) and 95% confidence interval (CI) show the effect of MMP-9 expression and age, tumour size, gender, lymph node metastasis (LNM), and TNM (tumour, lymph node, metastasis) stage." (PMID 37496069, 2023). "This retrospective study was designed to underpin the importance of MMP-9 and CCR7 expression in predicting the risk of lymph node metastasis in the LSCC patients." (PMID 37600570, 2023). "The researchers also observed a correlation between MMP-9 activation and the presence of lymph node metastasis, indicating its potential role in PTC metastasis." (PMID 38089632, 2023). "Low levels of serum melatonin and high levels of serum MMP-9 were correlated with larger tumor sizes and higher invasiveness and lymph node metastasis." (PMID 34945828, 2021). "In a study of 178 gastric tumor biopsies, the expression of BMP-2 and Matrix metallopeptidase (MMP)-9 showed a significant positive correlation with lymph node metastasis and a poor prognosis." (PMID 34001012, 2021). "• Promote tumor growth and angiogenesis in HNSCC. • Correlated with the expression of Snail and MMP9. • Correlated with recurrence, lymph node metastasis, and the worst prognosis in HNSCC patients." (PMID 35048028, 2021).